IL18 (interleukin 18)
Diseases named in the same sentence as IL18 in open-access papers (continued):
Sharing a sentence is not in itself a finding about the gene and the disease.
glioma (continued). "Considering the fact that berberine significantly attenuates the production of IL-18 and IL-1β, which are normally highly expressed in gliomas, we questioned if berberine treatment would significantly decrease the viability of glioma cells." (PMID 31139563, 2019). "Due to the histopathological heterogeneity of gliomas, mRNA levels of IL-1β and IL-18 in gliomas were analyzed according to the WHO grade system and histology." (PMID 31139563, 2019). "In this study, we demonstrate that berberine significantly inhibits inflammatory cytokine Caspase-1 activation via ERK1/2 signaling and subsequent production of IL-1β and IL-18 by glioma cells." (PMID 31139563, 2019). "In microglia sorted from rat C6 gliomas, genes characteristic for M1 activation: Tlr2, Tlr4 and Il18, Cd80, Il12a, Il15 were significantly downregulated." (PMID 29242629, 2017). "Systemic or intracerebral administration of IL-18 inhibited the growth of inoculated glioma cells and prolonged the survival of mice with subcutaneous or brain tumors, respectively." (PMID 20113500, 2010). "Antitumor activity against glioma was also found in mice treated with IL-18 and IL-12 via Semliki Forest virus or with a combination of IL-18 and Fas." (PMID 20113500, 2010). "In this respect, IL-18 was investigated alone or in synergism with IL-12 or Fas, for its ability to induce INFγ and NO inducing a cytotoxic response against glioma cells." (PMID 20113500, 2010). "Therefore, changes in IL-18 levels can serve as an indicator of disease severity and prognosis in glioma patients." (PMID 40656950, 2025). "However, the precise mechanisms by which IL-18 functions in glioma require further investigation to elucidate its dual roles in tumor biology and immune responses, thereby informing clinical treatment strategies." (PMID 40656950, 2025). "Furthermore, the IL-18 signaling pathway plays a significant role in glioma development by influencing tumor immune evasion mechanisms." (PMID 40656950, 2025). "Furthermore, IL-18 is highly expressed in the serum and tissues of glioma patients, indicating its potential involvement in glioma pathogenesis." (PMID 40838069, 2025). "However, another study reported that microglia secrete IL‐18 to promote migration of glioma in the tumor microenvironment." (PMID 36161280, 2023). "Among these pathways, many immune-related pathways were highly associated with PROS1, including CD22 mediated by regulation,immunoregulatory-Internation, chemokine receptors bind chemokines, disease of the immune system, chemokine signaling pathway, IL-18 signaling pathway in glioma." (PMID 36685506, 2022). "Since our clinical study confirmed that glioma samples have an upregulated protein expression of IL-1β and IL-18, we questioned whether inhibition of the production of IL-1β and IL-18 leads to glioma cell death." (PMID 31139563, 2019). "Previous studies have demonstrated that DCs loaded with lysed tumor cells and IL-18 may induce Th1 responses against glioma antigens." (PMID 25780408, 2015). "Some groups have investigated the possibility that IL-18 could be used against glioma, a common and highly aggressive type of brain tumor with poor long-term prognosis." (PMID 20113500, 2010). "In terms of therapeutic strategies, IL-18 antagonists have demonstrated the potential to inhibit tumor growth in experimental models, indicating that modulating IL-18 levels or its signaling pathways may offer novel approaches to enhance treatment outcomes for glioma patients." (PMID 40656950, 2025). "Moreover, evidence suggests that IL-18 may influence glioma growth by modulating the inflammatory microenvironment associated with tumors." (PMID 40656950, 2025). "The q-PCR results showed that MSR1 (p < 0.05), IL18 (p < 0.05), SLC11A1 (p < 0.05), and C3AR1 (p < 0.05) were highly expressed in the glioma tissue compared with the normal tissues." (PMID 37370848, 2023).
glioma (continued). "We combined all tumor expression data from TCGA with GEPIA2 data and obtained differentially expressed genes that were correlated with CASP4 expression in gliomas, including GSDMD, CASP1, IL-18, and TLR2." (PMID 36713560, 2022). "The differential gene analysis in the current study showed that CASP4 expression is associated with several other important molecules of pyroptosis, including GSDMD, CASP1, IL-18, and TLR2, in gliomas." (PMID 36713560, 2022). "The IL-1β, IL-18, TNF-α, and other cytokines in microglia are released and act on glioma to promote tumor cell proliferation." (PMID 36713560, 2022). "Co-expression of IL-18 and IFN-β by bone marrow MSCs inhibited glioma growth in vivo and prolonged the survival of glioma-bearing rats." (PMID 33117154, 2020). "In glioma cells, IL-18 facilitates VEGF-induced migration and forms a positive feedback loop wherein VEGF can upregulate IL-18 expression via ERK1/2 signaling." (PMID 32993787, 2020). "In the TCGA, CGGA, and REMBRANDT datasets, we demonstrated that the expression of IL-1β and IL-18 were significantly increased in grade IV gliomas, compared to those in WHO grade II and grade III gliomas." (PMID 31139563, 2019). "Previous research has demonstrated the critical role of IL-18 in the tumor immune microenvironment, suggesting that PTX3 may be crucial in modulating the immune response in glioma." (PMID 40656950, 2025). "CGGA data analysis revealed that high levels of IL-18 or IL-6 mRNA predict a poor prognosis for glioma patients (data not shown)." (PMID 37734869, 2023). "It has been shown that by means of tumour-specific tropism of MSCs can be transduced to deliver anticancer agents such as interleukins (IL-2, IL-7, IL-18, and IL-12), TRAIL, and interferon (IFN-β and IFN-γ) directly to glioma sites to kill tumour cells or to regulate immune responses." (PMID 32981013, 2020). "Other drugs and proteins encapsulated in PLGA microspheres for the treatment of glioma include temozolomide, paclitaxel, imatinib mesylate for treating intracranial glioma xenografts, BCNU as an alternative for Gliadel, cisplatin, mitoxantrone interleukin-18 and 5-Fluorouracil." (PMID 20932320, 2010).
liver fibrosis (32 papers, 2012 to 2025). "In mice with NASH-associated liver fibrosis induced by a high-fat diet, Studies have shown that IL-18 promotes the progression of liver fibrosis." (PMID 39995661, 2025). "Circulating IL-18 levels are elevated in several inflammatory conditions, while data have also linked the cytokine to liver fibrosis." (PMID 40565198, 2025). "The expression of IL-18 in serum and liver tissue was induced by DNA vaccine of IL-18, reducing schistosome-associated liver fibrosis (SSLF)." (PMID 34177893, 2021). "Significant differences were found in platelet count, liver enzymes (ALT, AST, GGTP, ALP), inflammatory markers (CRP, IL-6, IL-18), fibrinogen, and markers of liver fibrosis (APRI, FIB-4, ElastPQ)." (PMID 40806277, 2025). "Taken together, these results implicate IL-18 signaling as an important mediator of diet-induced liver fibrosis and IL-18BP as a key endogenous modulator of this process." (PMID 41275524, 2025). "The activation of the NLRP3 inflammasome, on the one hand, produces IL-1β and IL-18, leading to liver fibrosis." (PMID 36900523, 2023). "Recent research has shown that as hepatic fibrosis progresses, macrophages induce the expression of IL-1β/IL-18." (PMID 36834849, 2023). "Here, elevated levels of the pyroptosis-related indicators GSDMD, IL-1β, and IL-18 were confirmed in both clinical specimens from liver fibrosis patients and CCl4-induced liver fibrosis mouse models." (PMID 36429008, 2022). "Here, augmented levels of pyroptosis-related indicators GSDMD, IL-1β, and IL-18 were verified in both liver fibrosis patients and CCl4-induced fibrotic mouse model." (PMID 36429008, 2022). "Immunohistochemical (IHC) analysis revealed that the expression of hepatic GSDMD, IL-1β, and IL-18 was significantly upregulated in patients with liver fibrosis compared to HCs." (PMID 36429008, 2022). "They show that CCL2, IL-18, and IL-33 are involved in distinct stages of the disease and, particularly, in the onset of the disease, as well as in the hepatic fibrosis that may occur during the chronicity." (PMID 40565198, 2025). "This review highlights a significant increase in infiltrating monocytes in diabetic livers, with hepatic macrophages shifting to a pro-inflammatory state, elevating IFN-γ, TNF-α, IL-1β, IL-15, and IL-18, promoting inflammation, and contributing to liver fibrosis." (PMID 40362271, 2025). "Conversely, other studies suggest that IL-18 can enhance hepatic fibrosis and injury." (PMID 40243151, 2025). "Paired with work demonstrating the role of IL-18 in the development of pulmonary and hepatic fibrosis and the understanding that chronic meningitis leads to fibrosis of the meninges, IL-18 elevation in SANCC CSF may be relevant to the development of SANCC." (PMID 41013452, 2025). "Furthermore, the role of IL-18 in activating HSCs and fostering liver fibrosis has been demonstrated, as the antagonism of IL-18 reduces collagen deposition and enhances metalloproteinase activity in myeloid-specific NLRP3 gain-of-function mutant mice." (PMID 39770566, 2024). "In the present study, of the seventy-four systemic inflammatory molecules analyzed, five were statistically significantly associated with the stage of liver fibrosis: MCP.4 (p = 0.032), CCL19 (p = 0.024), EN.RAGE (p = 0.014), SCF (p = 0.01), and IL18 (p = 0.054)." (PMID 37317244, 2023). "When NLRP3 or ARRB2 was successfully silenced, as detected using real-time qPCR and Western blot, we analyzed the mRNA and protein levels of genes related to inflammation and liver fibrosis, including IL-1β, IL-18, p-NF-κB, COL III, FN, and α-SMA in LX-2 cells." (PMID 36983568, 2023). "In addition to hepatic stellate cells, infiltrated eosinophils have been shown to induce secretion of pro-inflammatory cytokines IL-18 and IL-1β, or even pyroptotic cell death of hepatocytes, leading to liver fibrosis." (PMID 35673561, 2022).
liver fibrosis (continued). "In addition, an in vitro mechanistic study showed that the pyroptosis products IL-1β and IL-18 regulate the activation of hepatic stellate cells (HSCs) and facilitate the development of liver fibrosis." (PMID 36429008, 2022). "Furthermore, serum S100A8 and pyroptosis-related indicators GSDMD, IL-1β, and IL-18 levels were all gradually augmented during the progression of the liver fibrosis model." (PMID 36429008, 2022). "Furthermore, serum levels of GSDMD, IL-18, and IL-1β were markedly enhanced in mouse models of liver fibrosis." (PMID 36429008, 2022). "In addition, a recent study confirmed that IL-18 can directly promote the activation of hepatic stellate cells in mouse liver fibrosis." (PMID 36361872, 2022). "However, uric acid is also one of the damage-associated molecular patterns (DAMP)-activated proinflammatory cytokines, similar to IL-1b, and IL-18 secretion and activated hepatic stellate cells induced liver fibrosis." (PMID 36556230, 2022). "Serum P III NP levels increase with the synthesis of collagen fibers in the liver, and these levels were found to be significantly increased in patients with liver cancer, suggesting that IL‐18 may be involved in the process of liver fibrosis." (PMID 33720453, 2021). "The direct regulation mainly occurs through inflammasome expression in hepatic stellate cells (HSCs) to promote hepatic fibrosis, and the indirect pathway for liver fibrosis is regulated by inducing IL-1β and IL-18 secretion in hepatic macrophages to promote HSC activation." (PMID 31429707, 2019). "Thus, IL-18 directly influences HSC activation and may serve as a target for IL-18-based therapies for liver fibrosis." (PMID 39689154, 2025). "In the mouse model of liver fibrosis induced by thioacetamide, ginsenoside was shown to inhibit the entry of IL-1β and IL-18 into the extracellular matrix by regulating ERRα-P2X7r signaling pathway, thereby reducing inflammatory responses, improving hepatocyte damage, and suppressing liver fibrosis." (PMID 39995661, 2025). "Furthermore, IL-18 could serve as a therapeutic target and potential biomarker for the prognosis of liver fibrosis." (PMID 39995661, 2025). "Recombinant IL-18 protein accelerates the trans-differentiation of primary murine HSCs into myofibroblasts, promoting ECM deposition and contributing to liver fibrosis." (PMID 40243151, 2025). "Liver fibrosis levels were flagrantly higher (p<0.01), and TNF-α, NOD-like receptor protein 3 (NLRP3), caspase-1, interleukin-18 (IL-18), and interleukin-1β (IL-1β) protein or gene expression were manifestly up-regulated (p<0.01)." (PMID 35195182, 2022). "Considering the pathogenic importance of NLRP3 inflammasome-induced pyroptosis in liver fibrosis, we measured the levels of key markers for pyroptosis, including NLRP3, pro-caspase-1, cleaved Caspase-1, cleaved GSDMD-N, IL-1β, and IL-18." (PMID 34839365, 2021). "A recent study found that, in a mouse model of CCl4-induced liver fibrosis, the Citrus aurantium extract astragalin inhibited the expression of TNF-α, IL-18, and IL-1β mRNAs in the livers of fibrotic mice through the NF-κB/NLRP3 inflammasome pathway, significantly ameliorating liver fibrosis." (PMID 39995661, 2025). "In vitro studies show that IL-1β and IL-18 regulate HSC activation and promote hepatic fibrosis." (PMID 36834849, 2023). "Based on the role of S100A8-elicited NLRP3 pyroptosis in liver fibrosis, we chose a well-defined cohort of liver fibrosis patients to assess the clinical importance of circulating S100A8, GSDMD, IL-1β, and IL-18 for predicting the occurrence and progression of disease." (PMID 36429008, 2022).
liver fibrosis (continued). "PA could also significantly up-regulate SOD and GSH-px levels (p<0.01), down-regulate IL-1β, IL-18, caspase-1, NLRP3, and TNF-α protein or gene expression in PBC mice (p<0.01) and inhibit liver fibrosis levels (p<0.01)." (PMID 35195182, 2022). "Regarding the prediction of post-KPE prognosis, a higher serum IL-18 level indicates the occurrence of persistent jaundice; an increased value of APRi, preoperative serum MMP-7 level or postoperative serum HA level predicts the occurrence of significant liver fibrosis." (PMID 34083585, 2021). "Moreover, good evidence was shown in investigations of serum IL-18 and IL-33 in distinguishing BA from healthy controls, serum IL-18 for prognosis of post-KPE persistent jaundice, and serum hyaluronic acid and MMP-7 for prognosis of post-KPE significant liver fibrosis." (PMID 34083585, 2021).
Alzheimer disease (31 papers, 2012 to 2025). A progressive, neurodegenerative disease characterized by loss of function and death of nerve cells in several areas of the brain leading to loss of cognitive function such as memory and language. "In particular, elevated IL-1Ra is found to be associated with poorer cognition in BD and IL-18 is associated with cognition although with mixed directions in Alzheimer’s disease and SCZ." (PMID 35082268, 2022). "In the cerebrospinal fluid of Alzheimer's disease patients, abnormally elevated levels of IL-1β and IL-18 were detected." (PMID 38317229, 2024). "The NLRP3 inflammasome is also a key element in Alzheimer’s disease (AD); its activation induces increased synthesis of pro-IL-1β and pro-IL-18 and activates caspase-1." (PMID 38928621, 2024). "IL-18, a marker of neuronal dysfunction, is elevated in cerebrospinal fluid in neurodegenerative conditions like Alzheimer’s disease and neuroinfectious diseases such as bacterial meningitis and human immunodeficiency virus-related dementia." (PMID 39816309, 2024). "High IL-1β and IL-18 levels were detected in patients with CNS infection, brain injuries, Alzheimer’s disease, and multiple sclerosis." (PMID 36675440, 2023). "IL-1β is known to play an important role in the pathological process of PND, and IL-18 can influence the integrity of neurons and increase neuroinflammation in the brain, thus leading to cognitive deterioration in Alzheimer's disease." (PMID 36406365, 2022). "Recently, Schipke and colleagues proposed the combined measurement of six different blood markers, BDNF, IGF-1, VEGF, TGF-beta 1, MCP-1 and IL-18 to identify Alzheimer’s disease patients." (PMID 32098256, 2020). "A recent meta-analysis study reported significantly higher levels of the proinflammatory cytokines TNF-α, IL-6, IL-1β, IL-2, and IL-18 in peripheral blood samples of patients with Alzheimer's disease (AD) compared with a control group." (PMID 30510525, 2018). "Caspase-1 and IL-18 have also been shown to be produced in neurodegenerative diseases such as Alzheimer's disease and Multiple sclerosis." (PMID 28861067, 2017). "In Alzheimer’s Disease, increased IL-21 levels lead to increased expression of MHC II in spleen Mφ and secretion of a large number of pro-inflammatory cytokines such as IL-18, TNFα and IL-1β." (PMID 37628738, 2023). "The upsurge in circulating IL-18 levels may signify a state of chronic inflammation within the brain, and its overexpression could potentially trigger tau protein phosphorylation, consequently contributing to neurodegeneration in Alzheimer's Disease (AD) patients." (PMID 38260156, 2023). "Furthermore, monocytes isolated and cultured from Alzheimer's disease patients exhibited increased gene expression of NLRP3, along with the cytokines IL-1β and IL-18, indicating heightened peripheral NLRP3-mediated immune responses in Alzheimer's disease progression." (PMID 38317229, 2024). "MaR1 promoted inflammation resolution by inhibiting chemotaxis, TNFα, IL1β, IL18 levels and NLRP3 inflammasome or NF-kB activation and regulating microglia activation in rodent models of Alzheimer’s disease, non-compressive lumbar disc herniation or inflammatory pain." (PMID 36670960, 2022). "While we included leptin, IL-6, IL-1β, TNF-α, and CRP, we did not assess other cytokines such as MCP-1, IL-18, or markers of microglial activation and phenotype (e.g., CD68 and sTREM2), which may play significant roles in glial reactivity in Alzheimer's disease." (PMID 40521397, 2025).